MTOR (mechanistic target of rapamycin kinase)
Diseases named in the same sentence as MTOR in open-access papers (continued):
Sharing a sentence is not in itself a finding about the gene and the disease.
asthma (81 papers, 2012 to 2026). "Its therapeutic effect is associated with the modulation of PI3K/Akt/mTOR signaling pathway activity and the regulation of excessive autophagy, which provides new potential approaches and mechanistic insights for asthma treatment." (PMID 41693773, 2026). "We next tested the role of MTOR using this time-dependent IL-13 model in the development and maintenance of airway mucous cell metaplasia associated with severe asthma." (PMID 40446022, 2025). "In summary, these findings point to IL-13–dependent and –independent roles of MTOR signaling in the development of pathogenic epithelial changes contributing to airway obstruction in severe asthma." (PMID 40446022, 2025). "In particular, it is thought that SBP corrects the balance of Th1/Th2 cells and alleviates the symptoms by inhibiting PI3K/mTOR activity, a mediating mechanism of action of allergic diseases such as asthma caused by hypersensitivity immunity." (PMID 35889810, 2022). "This is a conclusion similar to the study results in that mTOR activation in asthma was positively correlated with loss of Th17/Treg and Th1/Th2 balance." (PMID 35889810, 2022). "Conclusively, lncRNA PVT1-miR-15a-5p/miR-29c-3p-PI3K-Akt-mTOR axis was implicated in ozone-induced asthma development by promoting ASMC proliferation and Th1/Th2 imbalance." (PMID 33223504, 2020). "Being implicated in immune function, the mTOR pathway have a role also in asthma: during asthma onset mTOR is activated and during remission suppressed." (PMID 32102344, 2020). "In eosinophil-related research, the loss of mTOR can lead to autophagy activation, which has been observed in the peripheral blood eosinophils of severe asthma patients." (PMID 29720621, 2018). "The mTOR pathway has been implicated in immune functions; however, its role in asthma is not well understood." (PMID 28674387, 2017). "Treatment with mTOR inhibitors restored the IL-17/TGF-β ratio in the asthmatic mice, suggesting that inhibiting mTOR pathway activation reversed the loss of Th17/Treg balance during asthma onset." (PMID 28674387, 2017). "In patients experiencing asthma, mTOR activation was positively correlated with the loss of Th17/Treg and Th1/Th2 balance." (PMID 28674387, 2017). "Taken together, mTOR pathway activation positively correlated with the loss of Th1/Th2 balance and the loss of Th17/Treg balance during asthma onset, and inhibiting mTOR with mTOR pathway inhibitors restores these balances." (PMID 28674387, 2017). "Here, we sought to define the role of mTOR signaling on the pathogenic manifestations of asthma using a clinically relevant house dust mite (HDM)-induced model of murine disease." (PMID 22685525, 2012). "Similarly, Perilla seed decoction has been found to alleviate airway hyperreactivity in cough variant asthma model rats via the PI3K/AKT1/mTOR signaling pathway." (PMID 40264707, 2025). "In asthma, mTOR activation is positively correlated with loss of Th17/Treg and Th1/Th2 balance." (PMID 35889810, 2022). "Therefore, the lncRNA PVT1/miR-15a-5p/PI3K-Akt-mTOR axis was implicated in asthma development by promoting Th1/Th2 imbalance." (PMID 35769905, 2022). "In addition, PI3K/Akt/mTOR signaling was a widely-recognized driver of airway inflammation and airway remodeling underlying asthma etiology." (PMID 33223504, 2020). "Similarly, mTOR in patients experiencing asthma was associated with the loss of Th1/Th2 balance, as the level of mTOR in the serum of these patients correlated positively with the level of IL-4 and negatively with the level of IFN-γ." (PMID 28674387, 2017). "Based on the pivotal role of mTOR signaling in the pathogenesis of asthma, we investigated whether the antiasthmatic effects of AS-IV were associated with the mTOR signaling." (PMID 29234390, 2017).
asthma (continued). "Based upon the important role of mTOR signaling in inflammatory and remodeling responses, we investigated whether rapamycin could be utilized to modify the pathogenic manifestations of asthma as well as provide new insights into disease pathogenesis." (PMID 22685525, 2012). "IL-13–mediated MTOR activation drives loss of control of airway epithelial cell proliferation, hypertrophy, and migration, contributing to airway wall thickening and formation of eGC (eGC), which are key features of mucous cell metaplasia found in severe asthma." (PMID 40446022, 2025). "It has recently emerged that drugs such as the mTOR inhibitor rapamycin (Rapa) may play a key role in the treatment of airway inflammation associated with lung diseases, such as chronic obstructive pulmonary disease, asthma, and cystic fibrosis." (PMID 35182368, 2022). "We demonstrated that mTOR pathway inhibitor treatment not only effectively reduced asthmatic markers, including airway remodeling, in mice but also suppressed the altered Th17/Treg and Th1/Th2 balances that are associated with asthma onset at the molecular level." (PMID 28674387, 2017). "PTGS2, IL10, CTSB, JAK2, and MTOR were significantly downregulated in alveolar lavage fluid with increasing asthma severity, while MMP9, GSK3B, BCL2, EGFR, and CCND1 were upregulated." (PMID 40160461, 2025). "Zisuzi Decoction ameliorates AHR and partially reverses airway remodeling through inhibition of PI3K/AKT1/mTOR, JAK2/STAT3, and HIF‐1α/NF‐κB signaling pathways, demonstrating effectiveness in cough‐variant asthma management." (PMID 41426510, 2025). "Pretreatment with allergen-specific mRNA-LNP vaccine and mTOR inhibitor modulates CD8+ T cell responses in experimental asthma." (PMID 40985871, 2025). "Metaplastic airway epithelium in asthma is characterized by many of the central features of MTOR activation: increased epithelial cell hyperplasia and cellular hypertrophy." (PMID 40446022, 2025). "In asthma, mTOR becomes activated through phosphorylation, disrupting the balance of Th17/Treg and Th1/Th2 cells." (PMID 39940325, 2025). "This suppression leads to a reduction in pro-inflammatory substances and inhibits the activation of the PI3K/mTOR pathway, and this is crucial for asthma treatment." (PMID 39940325, 2025). "Taken together, these findings indicate the central role of MTOR signaling in perturbing key features of epithelial control of cell size, organization, and differentiation that contribute to airway obstruction in asthma." (PMID 40446022, 2025). "First, MTOR phosphorylation of substrate RPS6 was increased along the epithelium from individuals with severe asthma, particularly in regions rich in GC." (PMID 40446022, 2025). "During ozone-induced asthma exacerbation, PVT1 activates the phosphatidylinositol 3-kinase (PI3 K)/AKT/mammalian target of rapamycin (mTOR) pathway by inhibiting the miR-15a-5p pathway, resulting in a reduced Th1/Th2 ratio that facilitates asthma progression." (PMID 40493320, 2025). "Here, we propose what we believe to be a new paradigm: that the balance of MTOR and autophagy determines the development, persistence, and resolution of airway mucous cell metaplasia found in severe asthma." (PMID 40446022, 2025). "Transcriptome analysis confirmed that upregulation of MTOR was also found in bronchial epithelial cells in asthma and COPD." (PMID 40160461, 2025). "Airways from individuals with severe asthma showed increased MTOR signaling by RPS6 phosphorylation, which was reproduced using an IL-13–activated model of primary human airway epithelial cells (hAEC)." (PMID 40446022, 2025). "Conversely, pathways of nucleotide metabolism, asthma, and mTOR signaling were significantly more abundant in the CA group (p < 0.05)." (PMID 39456970, 2024). "Pingchuanning decoction attenuates airway inflammation by inhibiting autophagy through PI3K/Akt/mTOR signaling pathway in asthma." (PMID 37090692, 2023).
asthma (continued). "Based on the results of western blot analysis, upregulation of Sestrin2 induced inactivation of AMPK and activation of the mTOR signaling pathway, while downregulation of Sestrin2 reversed these effects in ASMCs from the asthma group." (PMID 37662894, 2023). "Macrophage autophagy is implicated in the progression of asthma through several signaling pathways, such as MAPK, TLR4, and mTOR, regulating the polarization, inflammatory responses, and cell death." (PMID 37181813, 2023). "Modulation of Sestrin2 affected activation of the AMPK/mTOR pathway in ASMCs, and further, modulating the AMPK/mTOR pathway affected the role of Sestrin2 in asthma." (PMID 37662894, 2023). "PTBP1 can significantly affect airway inflammation and remodeling in asthma by modulating the PI3K/PTEN/AKT/mTOR/HIF-1/VEGF signaling pathways." (PMID 37717070, 2023). "Targeting PI3K/AKT/mTOR signaling has been found to attenuate asthma pathology and play a significant role in airways protection." (PMID 38106417, 2023). "Collectively, these data revealed that Sestrin2 played its role via activation of the AMPK/mTOR signaling pathway in ASMCs from the asthma group." (PMID 37662894, 2023). "Luteolin and pingchuanning decoction improves asthma inflammation by inhibiting autophagy via activation of PI3K/AKT/mTOR pathway." (PMID 37090692, 2023). "IL-4 as a cytokine of crucial effector Th2 in allergic asthma can also induce autophagy in B cells dependent on JAK signaling via an mTOR-independent, PtdIns3K-dependent pathway, which can aggravate asthma through multiple mechanisms." (PMID 37063888, 2023). "The mTOR signaling pathway produces inflammatory or immune imbalance in asthma, and it has been reported that inhibition of mTOR activity can restore corticosteroid sensitivity in COPD." (PMID 37296627, 2023). "According to the results of western blotting analysis, the AMPK signaling pathway was inactivated and the mTOR signaling pathway was activated in ASMCs from the asthma group." (PMID 37662894, 2023). "mTOR participates in the pathogenesis of various diseases such as liver disease, breast cancer, acute lung injury, Alzheimer’s disease, and asthma by regulating autophagy." (PMID 37090692, 2023). "Collectively, these data suggested that Sestrin2 induced alterations in the AMPK/mTOR signaling pathway in ASMCs from the asthma group." (PMID 37662894, 2023). "In an earlier study on asthma, mTOR signaling increased mitochondrial function in ASMC and thereby controlled remodeling." (PMID 36518817, 2022). "The signaling pathway PI3K/mTOR, which is considered to be important in the treatment of asthma, is also involved in the effects of SBP, which suggests that SBP is a promising potential target for the development of therapeutic agents." (PMID 35889810, 2022). "In ASMCs, the effect of IgE (immunoglobulin E) on mammalian target of rapamycin (mTOR) signaling and mitochondria dysfunction was reported in an asthma remodeling model." (PMID 36430467, 2022). "Two studies investigated the involvement of mechanistic target of rapamycin (mTOR) on eosinophil hematopoiesis and asthma pathogenesis." (PMID 34019141, 2021). "The same group subsequently investigated the function of mTOR in eosinophil differentiation and asthma pathogenesis using both genetic and pharmacological approaches." (PMID 34019141, 2021). "Research evidence points to an increased IL-4, Th17 and the levels of serum mTOR as playing a key role in asthma development." (PMID 34069141, 2021).
asthma (continued). "We found that Beclin-1 and LC3-II/LC3-I were increased while mTOR and p-mTOR were decreased in ovalbumin-induced asthma model rats." (PMID 32831860, 2020). "It has been demonstrated that the downstream mTOR plays a critical role in airway inflammation and airway hyperreactivity in asthma." (PMID 32627816, 2020). "For example, mTOR activation has been shown to be essential for asthma onset, and inhibition of mTOR with rapamycin can suppress IL-1 translation and reduce mRNA stability of SASP factors." (PMID 31849968, 2019). "We confirmed that mTOR signaling was dramatically activated in our asthma model, as phosphorylation of the mTOR downstream targets, S6RP, p70S6K, 4E-BP1, and mTOR 2481, was dramatically increased." (PMID 30873032, 2019). "A previous study showed that mTOR signaling was significantly activated in patients with asthma onset, and that the inhibition of mTOR by rapamycin remarkably attenuated airway hyper-reactivity and inflammation in asthmatic mice." (PMID 30873032, 2019). "In an OVA-induced asthma model, mTOR myeloid selectively deletion mice showed an increased level of inflammatory cells in BALF, and so were eosinophils." (PMID 29720621, 2018). "A role of mTOR in the onset of asthma has been proposed, and both the mTOR pathway and NF-kB are activated following TNFα/ IL-4 mediated stimulation in the bronchial epithelial cell line BEAS-2B." (PMID 29320511, 2018). "PI3K/Akt/mTOR signaling cascade is supposed to contribute to allergic airway inflammation in asthma models." (PMID 28420166, 2017). "The elevated levels of mTOR in asthmatic mouse models, together with the observation of mTOR activation in asthma patients, suggests that the mTOR pathway is turned on during asthma disease onset." (PMID 28674387, 2017). "We then used immunohistochemical (IHC) staining to examine activation of the mTOR pathway during asthma onset in the normal control, asthmatic, and budenoside-treated mice." (PMID 28674387, 2017). "In summary, mTOR is activated during asthma onset and suppressed during asthma remission, and inhibiting the mTOR pathway in asthmatic mice alleviates asthmatic markers and restores the balances of Th17/Treg and Th1/Th2 cytokines." (PMID 28674387, 2017). "In patients experiencing an asthma attack, the levels of serum mTOR correlated positively with the number of Th17 cells and negatively with the number of Treg cells." (PMID 28674387, 2017). "The activation of mTOR in asthmatic mice and reduced activation of mTOR in the budenoside treatment group suggests that the mTOR pathway was activated during asthma onset and suppressed when asthma was alleviated." (PMID 28674387, 2017). "To examine the correlation between mTOR signaling and asthma, we first compared the levels of mTOR activation in patients experiencing an asthma attack with those in remission, patients with community-acquired pneumonia, and healthy controls." (PMID 28674387, 2017). "Mice in the asthma group showed significantly higher levels of mTOR activation than those in the control group, and this elevated mTOR activation was significantly reduced with budenoside, LY294002, triciribine, or rapamycin treatment." (PMID 28674387, 2017). "The mTOR signaling pathway was activated in the asthma group, and suppression of mTOR activation led to an improvement in asthmatic phenotypes, demonstrating the requirement of mTOR activation for asthma pathogenesis." (PMID 28674387, 2017).
asthma (continued). "Consistent with the observation of elevated serum mTOR in patients experiencing asthma, the asthmatic mice showed significantly enhanced serum mTOR levels." (PMID 28674387, 2017). "More importantly, the reduced asthmatic markers in response to mTOR inhibitor treatments suggest that activation of the mTOR pathway is required for asthma disease onset." (PMID 28674387, 2017). "PI3K activation was highly induced in the asthma group and reduced in the mTOR inhibitor treatment groups, except for the triciribine treatment group, which showed the highest levels of p-PI3K." (PMID 28674387, 2017). "p-mTOR and p-p70S6k levels, highest in the asthma group, were decreased to similar levels in all treatment groups as a result of mTOR pathway suppression by the inhibitors." (PMID 28674387, 2017). "We found that patients experiencing an asthma attack, when compared with patients in asthma remission, showed significantly elevated serum mTOR pathway activation, increased Th17 cells and IL-4, and decreased Treg cells and IFN-γ." (PMID 28674387, 2017). "Our study demonstrated the requirement for mTOR in asthma disease onset and compared the effects of asthma treatment with rapamycin, LY294002, or triciribine to that of the standard budenoside treatment." (PMID 28674387, 2017). "This significant improvement in asthmatic markers by mTOR inhibitor treatment suggests that mTOR pathway activation is critical for asthma pathogenesis." (PMID 28674387, 2017). "Because the mTOR signaling pathway is required for asthma onset and progression, and because inhibiting mTOR activation restores the Th17/Treg balance, mTOR inhibitors such as rapamycin represent novel treatment options for asthma." (PMID 28674387, 2017). "Mice in the asthma group showed severe airway remodeling, which was improved with budenoside or mTOR pathway inhibitor treatment." (PMID 28674387, 2017). "Consistent with the activation of mTOR in patients experiencing an asthma attack, we observed significantly higher levels of p-PI3K, p-Akt, p-mTOR, and p-p70S6k in asthmatic mice than in the control and budenoside treatment groups." (PMID 28674387, 2017). "The inhibition of PKCδ by rottlerin is supposed to attenuate non-specific airway sensitivity and inflammation through suppressing the PI3K/Akt/mTOR pathway in an asthma model." (PMID 26633375, 2015). "The evidence suggests that the mTOR pathway is vital for airway and vascular remodeling, which is a key characteristic of severe asthma." (PMID 25478966, 2014). "On the other hand, cumulative evidence suggests that mTOR pathway is vital for airway and vascular remodeling, which is a key characteristic of severe asthma." (PMID 24312355, 2013). "At the cellular level, mTOR can physically interact with NF-κappaB or STAT1, both of which are associated with airway inflammation in asthma." (PMID 22685525, 2012). "We show that inhibition of mTOR signaling by rapamycin has paradoxical effects on the manifestations of HDM-induced asthma." (PMID 22685525, 2012). "Rapamycin attenuated the manifestations of HDM-induced asthma after 3 weeks in the induction model when mTOR signaling was increased, but exacerbated HDM-induced asthma after 6 weeks in the treatment model, when mTOR signaling had returned to basal levels." (PMID 22685525, 2012). "mTOR inhibition also has effects on other immune cells that participate in the pathogenesis of asthma." (PMID 22685525, 2012). "MTOR signaling is increased in severe asthma airways with mucous cell metaplasia." (PMID 40446022, 2025). "The first report on the role of MTOR in asthma mouse models was 20 years ago." (PMID 40446022, 2025). "DEHP may act through MTOR in asthma and COPD and participate in asthma inflammation and airway remodeling in COPD." (PMID 40160461, 2025). "Other studies have confirmed the importance of MTOR in type 2 models of asthma in mice." (PMID 40446022, 2025).